CFTR (CF transmembrane conductance regulator)
Diseases named in the same sentence as CFTR in open-access papers (continued):
Sharing a sentence is not in itself a finding about the gene and the disease.
pancreatic insufficiency (continued). "Certain CFTR mutations, such as R248/[H939;H949L], have been associated with hepatopathy characterized by elevated transaminase levels, typically observed in CF patients with good nutritional status and pancreatic insufficiency." (PMID 38611676, 2024). "Abnormal CFTR function in CF patients causes pancreatic ductular obstruction and may result in subsequent pancreatic insufficiency." (PMID 38229125, 2024). "Furthermore, the CFTR gene mutation also contributes to digestive system disturbances associated mainly with exocrine pancreatic insufficiency, biliary cirrhosis, sweat glands and reproductive system dysfunction." (PMID 37711888, 2023). "Some rare genetic variants of the CFTR gene may be associated with other diseases, such as bronchiectasis, pancreatic insufficiency and male infertility (CFTR-RDs)." (PMID 37761847, 2023). "The participants with CFRD were older than the participants from the CF control group (33 vs. 30 years, p = 0.05), presented more often with exocrine pancreatic insufficiency and with 2 severe CFTR mutations than the participants from the CF control group (p < 0.0001 and p = 0.003, respectively)." (PMID 37369827, 2023). "The pancreatic insufficiency prevalence (PIP) score is a practical approach to understanding how patients who carry CFTR variants with mild phenotypic effects have a greater risk of developing pancreatitis than those associated with moderate-to-severe phenotypes." (PMID 36832409, 2023). "The pancreatic insufficiency prevalence (PIP) score was calculated on CFTR mutations." (PMID 36832409, 2023). "A higher antigen load from increased intestinal permeability, inflammation, and pancreatic exocrine insufficiency secondary to CFTR dysfunction might be the leading cause." (PMID 35268004, 2022). "Beside the peculiar lung involvement, CFTR mutations also interest pancreatic and biliary duct cells, causing defective bile flow and thick biliary secretion, pancreatic exocrine insufficiency, and nutrients malabsorption, finally leading to diabetes mellitus and biliary fibrosis." (PMID 34248852, 2021). "Specifically, we tested for an association between the square-root-transformed age at the first P. aeruginosa infection and 17,139 SNPs in Chr 1 Mb 97.0 to 105.0 of hg19 in 712 individuals of European descent with severe CFTR genotypes known to be associated with pancreatic insufficiency." (PMID 32127447, 2020). "Despite the limitation of small sample size in our study, we showed that CF subjects with CFTR genotypes associated with pancreatic insufficiency were more likely to be colonized with P. aeruginosa or the mucoid form of P. aeruginosa than those with genotypes associated with pancreatic sufficiency." (PMID 28800122, 2017). "This genetic disorder, caused by a mutation of the CF transmembrane conductance regulator (CFTR) gene, is mostly characterized by recurrent lower respiratory infections, exocrine pancreatic insufficiency (85% of patients), and increased electrolyte concentration in sweat." (PMID 26770018, 2015). "Group 1 had a significantly higher frequency of homozygosity for the CFTR ∆F 508 mutation, pancreatic insufficiency, bronchial colonization with Pseudomonas aeruginosa, and biological inflammatory syndrome, and significantly lower body mass index (BMI) and longer disease duration (data not shown)." (PMID 24884656, 2014). "Since its initial description in a CF Canadian patient with pancreatic insufficiency, the mutation p.I148T, which changes a conserved amino acid and occurs in the first cytoplasmic loop of the CFTR protein, has been considered as a severe CF allele in many countries." (PMID 15287992, 2004). "Furthermore, the vast clinical spectrum correlated with CFTR gene mutations varies from severe classical CF with pancreatic insufficiency to delayed CFTR-related diseases such as bronchiectasis or male sterility, which is caused by a congenital bilateral absence of the vas deferens." (PMID 35886548, 2022).
pancreatic insufficiency (continued). "Whereas complete loss of CFTR function leads to the CF-typical fibrosis of the exocrine pancreas and pancreatic insufficiency, it has become clear in recent years that milder forms of CFTR dysfunction, whether congenital or acquired, are involved in the pathophysiology of pancreatitis." (PMID 35011616, 2021). "A primary and well-established driver of undernutrition in CF is exocrine pancreatic insufficiency (EPI), impacting approximately 85% of PwCF, and it is typically associated with severity of CFTR genetic mutation." (PMID 40806116, 2025). "We present the case of an adult woman diagnosed with CF at 12 years and 7 months (CFTR genotype: 3849 + 10 kbC > T)/3849 + 10 kbC > T, SC: 59 mmol/L) with pancreatic insufficiency, and recurrent chest infections." (PMID 40149127, 2025). "As expected, our results showed a greater HV increase in the F/F and F/MF patient groups, both of which are characterized by more severe CFTR genotypes and universal exocrine pancreatic insufficiency." (PMID 40806881, 2025). "The results also show a higher proportion of pancreatic insufficiency and CFTR modulator use among CFLD patients, reflecting the clinical complexity of managing such cases." (PMID 40807022, 2025). "We present the case of an adult man with CF (CFTR genotype: F508del/541DelC; sweat chloride (SC): 84–86 mmol/L) diagnosed at 4 months in the presence of pancreatic insufficiency and respiratory symptoms." (PMID 40149127, 2025). "Exocrine pancreas insufficiency and the use of highly effective CFTR modulator therapy with elexacaftor/tezacaftor/ivacaftor was more common in those with C. dubliniensis." (PMID 41143430, 2025). "Along with CFTR dysfunction, exocrine pancreatic insufficiency plays a key role in persistent fat malabsorption in CF patients; therefore, deficiency of fat-soluble vitamins (A, D, E, and K) is still a therapeutic challenge." (PMID 38229125, 2024). "Our study population showed an almost balanced sex ratio and the distribution of CFTR genotypes and proportion of exocrine pancreatic insufficiency was representative for CF patients in Central Europe." (PMID 38903825, 2024). "CFTR dysfunction adversely affects smooth-muscle contractility, leading to consequences such as pancreatic insufficiency, reduced bicarbonate, and fluid secretion, resulting in the formation of viscous secretions and fat malabsorption." (PMID 38275475, 2024). "As a result of the increased use of CFTR modulators, there are described three different patients groups with varying grades of pancreatic insufficiency and different response to therapy." (PMID 36678791, 2023). "Lipomatosis was more frequent in subjects with CFRD and was related to exocrine pancreatic insufficiency (EPI) and to severe CFTR mutations (classes I to III)." (PMID 37369827, 2023). "This is due to improved clinical treatments including earlier diagnosis of CF and pancreatic insufficiency and enhanced medical therapies including CFTR-targeted therapies." (PMID 35088244, 2022). "It is known that higher PAP values are in CRMS/CFSPID or CF patients with CFTR variants leading to pancreatic sufficiency, and low PAP values are in some patients with CFTR variants leading to pancreatic insufficiency and a severe CF phenotype." (PMID 35997436, 2022). "Risk factors for CFLD include male sex, the presence of two severe mutations (loss-of-function CFTR), presence of SERPINA 1Z allele, exocrine pancreatic insufficiency, and CFRD." (PMID 35268004, 2022). "It is more prevalent in patients with more severe defects of the cystic fibrosis transmembrane conductance regulator (CFTR) channel (like F508del mutation), those with exocrine pancreatic insufficiency, and the prevalence increases with age." (PMID 35455577, 2022). "Lower campesterol, β-sitosterol, total cholesterol and LDL-C levels were documented in patients with a severe CFTR genotype and exocrine pancreatic insufficiency." (PMID 33669566, 2021).
pancreatic insufficiency (continued). "We documented low phytosterol concentrations in CF patients with a severe CFTR genotype and exocrine pancreatic insufficiency." (PMID 33669566, 2021). "Campesterol and β-sitosterol concentrations were lower in patients with a severe CFTR genotype, pancreatic insufficiency and lower pancreatic enzyme dose (lipase units/gram of fat)." (PMID 33669566, 2021). "A female 13 months-old was affected by CF with pancreatic insufficiency, diagnosed through a positive NBS and two CF-causing mutations [F508del/4016insT] at CFTR genetic analysis." (PMID 32234058, 2020). "In the pancreas, CFTR abnormality results in abnormally viscous secretions that obstruct proximal ducts leading to fibrotic injury and ultimately pancreatic insufficiency in 85% of the CF population." (PMID 31296159, 2019). "The pancreatic insufficiency prevalence (PIP) scores, based on the exocrine pancreatic phenotype, have been shown to accurately distinguish the severity of different CFTR mutations." (PMID 31640630, 2019). "The available data show that the LA level was significantly lower in patients with severe CFTR mutations, with worse pulmonary function (lower FEV1 percentage) and pancreatic insufficiency." (PMID 28106773, 2017). "The multiple regression analysis of other n-6 FAs in our study showed that age, diabetes, CFTR genotype, liver disease and pancreatic insufficiency were all significant predictors of n-6 FAs’ abnormalities (GLA, C20:3n-6, C20:4n-6, C22:4n-6)." (PMID 28106773, 2017). "Pancreatic insufficiency or sufficiency is genetically determined, and the correlation between CFTR genotype and pancreatic phenotype is well established." (PMID 28800122, 2017). "C20:3n-9 levels were higher in patients with a severe CFTR genotype, exocrine pancreatic insufficiency, insufficient height and also in children." (PMID 28106773, 2017). "Although the regression analysis also pointed towards pancreatic insufficiency and CFTR genotypes as independent correlates of low DHA levels, our work does not identify these two factors as the main determinants of serum FA alterations in CF." (PMID 28106773, 2017). "In the combined GWAS1+2 data set, 99.8% of subjects were pancreatic exocrine insufficient (primarily defined by CFTR genotypes); 65.0% were p.Phe508del homozygotes; 95.5% were of European ancestry; and only 5.4% were diagnosed by newborn screening." (PMID 26417704, 2015). "It is caused by mutations in the CF Transmembrane conductance Regulator (CFTR) gene and mainly characterized by bronchopulmonary disease, pancreatic insufficiency and male infertility." (PMID 25503271, 2014). "G542X is a Class I mutation that results in the complete failure to synthesize functional cystic fibrosis transmembrane conductance regulator (CFTR) and is usually associated with pancreatic insufficiency." (PMID 20718961, 2010). "In a single-center, cross-sectional database analysis of adults with CF from 2015–2017, 25% of adults with severe CFTR genotypes (associated with pancreatic insufficiency and/or little to no functional protein) had BMI ≥ 25 kg/m2." (PMID 40806116, 2025). "Most participants (80.7%) received CFTR modulator therapy, and 86.9% had pancreatic insufficiency." (PMID 40941546, 2025). "Moreover, this patient subgroup also demonstrated higher incidences of pancreatic insufficiency and CFTR modulator use, suggesting a more severe disease phenotype." (PMID 40807022, 2025). "In conclusion, CFTR gene mutations were significantly associated with pancreatic insufficiency but not with disease severity." (PMID 36102402, 2022). "The objective of this study was to assess the composition patterns of free, taurine- and glycine-conjugated BAs from pwCF in regard to exocrine pancreatic insufficiency, according to recently defined CFTR genotype (pancreatic insufficiency prevalence [PIP] score) and CFLD classifications." (PMID 36293293, 2022).
pancreatic insufficiency (continued). "Exocrine pancreatic insufficiency in CF patients is mainly dependent on CFTR dysfunction." (PMID 33925519, 2021). "Pancreatic insufficiency: A severe CFTR gene mutation in both alleles results in little or no CFTR chloride channel activity and destruction of the exocrine pancreas." (PMID 34073663, 2021). "However, the broad phenotypic spectrum associated with mutations in the CFTR gene ranges from severe classical CF with pancreatic insufficiency to late onset CFTR-related disorders (CFTR-RD) such as bronchiectasis or isolated male infertility by CBAVD." (PMID 33946859, 2021). "Second, the dysfunctional cystic fibrosis transmembrane regulator (CFTR) gene contributes to pancreatic insufficiency and nutrient malabsorption which leads to diminished secretion of pancreatic enzymes, dysfunctional lipid digestion, and ultimately, reduced absorption of fat-soluble vitamins." (PMID 31320980, 2019). "Vitamin K deficiency defined as PIVKA-II ≥ 2 ng/ml was much more frequent in patients with pancreatic insufficiency, the genotype F508del/F508del or the severe mutations in both alleles of the CFTR gene, and those not receiving vitamin K." (PMID 26160248, 2015). "However, individuals with CF did not cluster based on carriage of Clostridium difficile, class of CFTR mutation, % predicted FEV1, pancreatic insufficiency, inpatient days or treatments received i.e. proton pump inhibitors, courses of IV antibiotics and macrolide antibiotic therapy (data not shown)." (PMID 28279152, 2017). "A 10-year-old girl with CF and pancreatic insufficiency was diagnosed via NBS (SC 97–103 mEq/L, CFTR genetic profile: F508del/F508del) according to the protocol used in Campania region, Italy." (PMID 40217771, 2025). "A systematic review demonstrated that CFTR modulators such as ivacaftor improved exocrine pancreatic function in pediatric patients, but data on the effects of ETI on exocrine pancreatic insufficiency in adults remain limited." (PMID 40806025, 2025). "A 13-year-old girl with CF and pancreatic insufficiency (SC 125–125 mEq/L, CFTR genetic profile: F508del/Deletion 22–24; false-negative at CF newborn screening (NBS)), was diagnosed at three years of age during hospitalization for complicated pneumonia." (PMID 40217771, 2025). "When measuring each BA individually, CA levels were significantly associated with more severe CFTR genotypes, as quantified by their PIP score for pancreatic insufficiency and non-cirrhotic CF-related liver involvement." (PMID 36293293, 2022). "We assess the pattern of serum BAs in people with CF (pwCF) without CFTR modulator therapy in regard to pancreatic insufficiency and the CFTR genotype." (PMID 36293293, 2022). "All the patients received dornase alfa, all patients with pancreatic insufficiency received pancreatic enzymes and none were treated with CFTR modulators." (PMID 32560275, 2020).
bronchiectasis (105 papers, 2008 to 2026). Segmental, irreversible dilation of the bronchial tree resulting in the accumulation of secretions which leads to obstruction. "A diagnosis was made of bronchiectasis caused by CFTR dysfunction, and he was treated with inhalation solution of dornase alfa, hypertonic saline solution, and tobramycin at the age of 25; however, his lung deteriorated, and he died at the age of 32." (PMID 40718166, 2025). "About 30% of patients with idiopathic chronic pancreatitis or recurrent acute pancreatitis have CFTR variants, and CFTR pathologic variants are found in 10–50% of bronchiectasis patients." (PMID 41373238, 2025). "Two were diagnosed with CFTR-RD, presenting with bronchiectasis, intermediate sweat test and a second mutation known to cause CFTR-RD." (PMID 40301948, 2025). "Defective CFTR is sufficient to drive these disease features in CF, and is linked to this microbial phenotype in a proportion of non‐CF bronchiectasis cases." (PMID 39358991, 2025). "A family-based association study highlighted that cystic fibrosis transmembrane conductance regulator (CFTR) gene mutations in RA patients are indicators of associated bronchiectasis risk." (PMID 38783321, 2024). "Cystic fibrosis transmembrane conductance regulator (CFTR) mutation results in the development of bronchiectasis, recurrent infectious exacerbations and lung function decline." (PMID 38807122, 2024). "CFTR modulator therapy was associated with improvements in structural lung disease and bronchiectasis assessed using PRAGMA-CF." (PMID 37113757, 2023). "It is an autosomal recessive inherited genetic disease caused by a mutation of the CFTR gene (CF Transmembrane Conductance Regulator) and exhibits chronic and fatal pathology due to bronchiectasis and progressive and obstructive pulmonary deterioration." (PMID 35271048, 2022). "After the selection of rare variations (minor allele frequency <1%) related to bronchiectasis, one homozygous variant of cystic fibrosis transmembrane conductance regulator (CFTR) was identified in each family." (PMID 34276759, 2021). "Several CF transmembrane conductance regulator (CFTR) variants have been shown to occur at a higher frequency among patients with bronchiectasis or NTM-PD than among healthy controls." (PMID 34835346, 2021). "As CFTR is mainly expressed in various glandular tissues, the variants can cause abnormal ion transport and secretory function, subsequently leading to bronchiectasis, pancreatic insufficiency, and fertility dysfunction in males." (PMID 34276759, 2021). "Studies have shown that heterozygosity for CFTR has pathogenic consequences and contributes to the development of bronchiectasis." (PMID 35096640, 2021). "The two patients we described here have nasosinusitis, bronchiectasis, high levels of chloride in sweat, and CFTR gene mutations, and the male patient is infertile due to a vas deferens abnormality; therefore, CF was diagnosed." (PMID 32454915, 2020). "CFTR mutations, often with unclear pathogenic effect, have been reported with higher frequency among patients with bronchiectasis." (PMID 30151190, 2018). "Using our in‐house next‐generation sequencing (NGS) pipeline for childhood bronchiectasis, we identified disease‐causing CFTR mutations in CF patients in Hong Kong." (PMID 28116329, 2017). "Here, we have identified three patients with bronchiectasis who are trans-heterozygotes for ENaCβ/CFTR mutations or variants, and these cases strongly suggest an interaction between different susceptibility factors in the pathogenesis of their airway disease." (PMID 18507830, 2008). "Both heterozygosity for L997F and compound heterozygosity for other CFTR mutations have been associated with idiopathic disseminated bronchiectasis, recurrent pancreatitis, and hypertrypsinemia in infants." (PMID 18501000, 2008).